ENSG00000288625 (novel protein)
Synonyms: LOC128071545
Gene: Protein-coding gene on chromosome 15 (81,002,142 to 81,002,279, forward strand). Ensembl gene ENSG00000288625.
Genetic constraint (gnomAD): Missense variants: 22 observed, 32.61 expected, observed/expected ratio (o/e) 0.67, 90% interval 0.48 to 0.96. Synonymous variants: 16 observed, 12.36 expected, observed/expected ratio (o/e) 1.29, 90% interval 0.87 to 1.84.